TNFRSF11A (TNF receptor superfamily member 11a)
Diseases named in the same sentence as TNFRSF11A in open-access papers (continued):
Sharing a sentence is not in itself a finding about the gene and the disease.
amyotrophic lateral sclerosis (1 paper, 2022). Amyotrophic lateral sclerosis (ALS) is a neurodegenerative disease characterized by progressive muscular paralysis reflecting degeneration of motor neurons in the primary motor cortex, corticospinal tracts, brainstem and spinal cord. "Additionally, some cases of PDB-like syndromes have been attributed to mutations in VCP, TNFRSF11A, TNFRSF11B, HNRNPA2B1, HNRNPA1, ZNF687 and PFN1, most of which are known to involved in the amyotrophic lateral sclerosis (ALS) and nuclear factor kappa B (NF-kB) signaling pathways." (PMID 35355568, 2022).
cervical squamous cell carcinoma (1 paper, 2017). A squamous cell carcinoma arising from the cervical epithelium. "Notably, tumour necrosis factor (TNF)-α induced KLF5 expression by activating the p38 signalling pathway and high KLF5 and TNFRSF11a expression increased the risk of death in patients with cervical squamous cell carcinoma." (PMID 29146991, 2017). "In this study, we demonstrated that both TNFRSF11a and KLF5 were strongly expressed in HeLa and SiHa cells and human cervical squamous cell carcinoma (CSCC) tissues." (PMID 29146991, 2017).
cervical tumours (1 paper, 2017). "We initially observed KLF5 and TNFRSF11a mRNA and protein coexpression in cervical tumours, and identified KLF5 as an effector of TNFRSF11a." (PMID 29146991, 2017).
chronic kidney disease (1 paper, 2025). Impairment of the renal function secondary to chronic kidney damage persisting for three or more months. "Both Tnfrsf11a and Zc3h12c are highly expressed in the kidney tissue from patients with chronic kidney disease and showed a positive association with an interstitial fibrosis score." (PMID 40834429, 2025).
colorectal adenocarcinoma (1 paper, 2019). The most common type of colorectal carcinoma. "Colorectal adenocarcinoma cases were analysed for associations between GFI1 or TNFRSF11A mRNA expression and clinicopathological features." (PMID 30858927, 2019).
colorectal tumour (1 paper, 2019). "This study then utilized RNAscope® to quantify mRNA expression of candidate prognostic markers GFI1 and TNFRSF11A, and analysed their association with clinicopathological features from FFPE colorectal tumour tissue." (PMID 30858927, 2019). "Having established RNAscope® as a technical comparable method to immunohistochemistry, this study successfully utilized RNA in situ hybridisation (RNAscope®) to quantify mRNA expression of candidate prognostic markers GFI1 and TNFRSF11A from FFPE colorectal tumour tissue." (PMID 30858927, 2019). "Furthermore, this study quantified intra-tumoural expression of GFI and TNFRSF11A in different cell types present within the colorectal tumour tissue." (PMID 30858927, 2019).
coronary aneurysm (1 paper, 2021). Abnormal balloon- or sac-like dilatation in the wall of coronary vessels. "Patients with KD were then divided into CAA group and NCAA group according to whether they had coronary aneurysm (CAA) or not, and TNFRSF11A rs7239667 genotyping was performed in the two groups." (PMID 34484292, 2021). "In addition, the patients with KD were divided into CAA and NCAA groups according to whether they had coronary artery aneurysm (CAA) or not, and the TNFRSF11A rs7239667 genotyping was performed in the two groups." (PMID 34484292, 2021).
dysosteosclerosis (1 paper, 2022). Dysosteosclerosis is a skeletal dysplasia characterized by progressive osteosclerosis and platyspondyly. "Clinical and radiographic findings of TNFRSF11A-associated dysosteosclerosis." (PMID 35812760, 2022).
glaucoma (1 paper, 2023). Increased pressure in the eyeball due to obstruction of the outflow of aqueous humor. "TNFRSF11A is a target of diclofenac, an anti-inflammatory drug used to treat glaucoma, and TNFSF11 is a target of lenalidomide, denosumab, and anastrozole." (PMID 37893075, 2023).
Lymphadenopathy (1 paper, 2022). Enlargement (swelling) of a lymph node. "Chromosomal rearrangement (18q21.3-q22.2 dup/18q22.2-qter del) encompassing a duplication of TNFRSF11A has been reported to be associated with recurrent fever, rash and lymphadenopathy." (PMID 35897075, 2022).
optic atrophy (1 paper, 2022). A disorder characterized by loss of optic nerve fibers. "DSS from compromised TNFRSF11A can lead to optic atrophy as an early finding." (PMID 35991533, 2022).
ovarian failure (1 paper, 2015). "For example, TNFRSF11A (also known as RANK) plays a key role in apoptosis and is up-regulated in mice with environmental toxin induced ovarian failure." (PMID 25682867, 2015).
tumor (251 papers, 2003 to 2026). "Consistent with the TCGA Network study, we found reduced GFI1 expression was associated with high-grade and left-sided tumours, and reduced TNFRSF11A expression was associated with metastasis and high nodal involvement." (PMID 30858927, 2019). "The expression level of TNFRSF11A (RANK) in MPs cells was highest in LC-BoM compared to other tumor tissues." (PMID 41362730, 2026). "The expression level of TNFRSF11A (RANK) in TAMs was highest in LC-BoM compared to other tumor tissues." (PMID 41362730, 2026). "In vitro experiments demonstrated that EFNB2, PTTG1IP, and TNFRSF11A were upregulated in dormant tumor cells, which also contributed greatly to the diagnosis of LUAD." (PMID 39273449, 2024). "All primary HRS cells specifically expressed TNFRSF8 (CD30) and most HRS and bystander cells expressed CD40, highlighting the quality of our data However, only a subset of tumours expressed LTR-driven TNFRSF11A and WNT5A transcripts." (PMID 30546079, 2019). "We observed both homogenous and heterogeneous GFI1 and TNFRSF11A mRNA expression patterns across the tumour cohort." (PMID 30858927, 2019). "To better characterise the intra-tumoural expression patterns of GFI1 and TNFRSF11A, we used RNAscope® to quantify mRNA levels across 10 whole tumour sections according to tumour cell type." (PMID 30858927, 2019). "In this model, TNFRSF11a knockdown significantly suppressed HeLa tumour growth, leading to lower mean tumour weights and few liver metastases after 28 days." (PMID 29146991, 2017). "TNFRSF11A is up-regulated in an average of 75% of HRS cells from primary tumour samples." (PMID 30546079, 2019). "Although these results may be significant, they are rather generalised and further study is needed to confirm the expression of KLF5 and TNFRSF11a mRNA and protein in clinical CC tumours." (PMID 29146991, 2017). "A potential role for TNFRSF11a in tumour cell proliferation is being investigated; if proven, this molecule could be a future target of anti-tumour therapies." (PMID 29146991, 2017). "Additionally, we did not observe an association between TNFRSF11A and tumour stage or distant metastasis." (PMID 30858927, 2019). "The tumor necrosis factor (TNF) receptor superfamily member 11a (TNFRSF11a, also known as RANK) was demonstrated to play an important role in tumor metastasis." (PMID 33795653, 2021). "Noteworthy, several studies identified novel RANK isoforms generated through alternative splicing of the RANK gene (TNFRSF11A: TNF Receptor Superfamily Member 11a), further increasing the functional complexity of RANKL/RANK system in normal and tumor cells." (PMID 30621730, 2019). "In this study, we demonstrated a potential role for tumour necrosis factor receptor superfamily member 11a (TNFRSF11a), the corresponding gene of which is a direct binding target of KLF5, in tumour cell proliferation and invasiveness." (PMID 29146991, 2017). "Significant differences in tumour size, histological type, invasion depth, nodal metastasis status, pathological grade, Union for International Cancer Control (UICC) stage and disease-free survival outcomes were detected between the two KLF5 groups and TNFRSF11a groups (P < 0.05)." (PMID 29146991, 2017).
cancer (138 papers, 2007 to 2025). A tumor composed of atypical neoplastic, often pleomorphic cells that invade other tissues. "Aberrant TNFRSF11A (RANK) expression has been linked to several cancers." (PMID 36230614, 2022). "TNF receptor superfamily member 11a (RANK) and its ligand TNF superfamily member 11 (TNFRSF11, RANKL) have also been linked to cancer." (PMID 38902257, 2024). "The mean expression levels for TNFRSF11A in carcinoma cells was 7-fold higher than surrounding cell types (0.35 vs 0.05 signals/cell; CI 0.09 – 0.51, P = 0.009)." (PMID 30858927, 2019). "Functionally, KLF5 promoted cancer cell proliferation, migration and invasiveness in a manner dependent partly on TNFRSF11a expression." (PMID 29146991, 2017). "This analysis showed that mean GFI1 and TNFRSF11A mRNA expression levels within carcinoma cells were significantly higher compared to other cell types (F = 14.86, P = 1.89E-08 and F = 10.27, P = 1.11E-06), including normal epithelial cells, stromal fibroblasts and lymphocytes." (PMID 30858927, 2019). "LINC00261, TNFRSF11A, CASP1, ST6GALNAC1, and PIGR also play prognostic roles in cancer." (PMID 31689990, 2019).
infection (23 papers, 2012 to 2026). The state of being infected such as from the introduction of a foreign agent such as serum, vaccine, antigenic substance or organism. "To further investigate whether KLF5 is an effector of TNFRSF11a and whether KLF5 plays a role in TNF-α-induced CC cell functions, we overexpressed KLF5 in HeLa cells through infection with a specific adenovirus (Ad-KLF5)." (PMID 29146991, 2017).
cardiovascular disease (13 papers, 2014 to 2025). "In 2023, a proteomics study identified 233 plasma proteins related to cardiovascular disease and inflammation, pinpointing 21 proteins associated with kidney function decline, among others, such as TNFRSF11A." (PMID 38540220, 2024).
bone disorder (10 papers, 2011 to 2025). "Eight AFF patients (NS2‐9) without a clinical suspicion of a monogenic bone disorder carried one or more heterozygous VUS with a CADD score ≥ 20 in P4HB, PHEX, TNFRSF11A, CREB3L1, TCIRG1, SERPINH1, LEPRE1, and PLOD2." (PMID 37076969, 2023).
skeletal dysplasia (2 papers, 2007 to 2026). Any Mendelian diseases that affects growth and development of the skeleton. "Mutations in the genes encoding some of the molecules in these pathways, including RPS6SKA3, LIFR, TNFRSF11A and IKBKG, have been associated with human skeletal dysplasias, again suggesting that the remaining genes may also serve critical roles in endochondral ossification." (PMID 17565682, 2007).
TNFRSF11A also shares sentences with these, for which no sentence is quoted: periodontitis (54 papers); prostate carcinoma (41); diabetes (27); Arthritis (26); melanoma (25); multiple myeloma (23); Obesity (16); bone metastasis (14); periodontal disease (13); osteoarthritis (12); Osteopenia (12); Autoimmunity (11); osteonecrosis (11); postmenopausal osteoporosis (10); sarcopenia (10); autoimmune disease (9); endometrial cancer (8); heart failure (8); Peri-Implantitis (8); bacterial infection (7); bone tumors (7); juvenile Paget disease (7); apical periodontitis (6); breast adenocarcinoma (6); colitis (6); liver disease (6); renal cell carcinoma (6); Sepsis (6); gastric cancer (5); glioma (5).
A further 232 diseases each share a sentence with TNFRSF11A in 5 papers or fewer.